IGF2 (insulin like growth factor 2)
Diseases named in the same sentence as IGF2 in open-access papers (continued):
Sharing a sentence is not in itself a finding about the gene and the disease.
cancer (continued). "Because IGF2 secreted from cancer cells may stimulate surrounding macrophages and fibroblasts in a paracrine manner, we next assessed the effect of CM from NNK-stimulated BEAS-2B cells on THP-1 and Wi38 cells." (PMID 37258578, 2023). "IGF2 is a crucial factor for cancer development and progression and promotes cell migration and invasion, so its downregulation could contribute to the observed phenotypes in invasive CRC cells." (PMID 37340282, 2023). "Overall the genomic landscape was stable, with pathogenic or likely pathogenic alterations being identified in 51 cancer genes, with 9 (18%) of them showing alterations being recurrent across different samples (MYCN, CDKN2A/2B, CDK4, GLI1, AKT1, IGF2, MED12, NCOR2)." (PMID 37730754, 2023). "Indeed, a number of studies have shown that the human IGF2 promoter usage in cancer switches from monoallelic p2–p4 IGF2 control to biallelic IGF2 expression under p1 control during tumorigenesis." (PMID 37371750, 2023). "Together with Afp and Igf2, the expression of stem cell markers Dlk1, Gpc3 and Epcam appeared to be higher in clusters 7 and 16, which may represent the bona fide cancer cells." (PMID 37414763, 2023). "This dysregulation is associated with cancer development, where LOI of IGF2 has been observed." (PMID 38001653, 2023). "IGF2 is crucial for carcinogenesis and aids in the development of cancer." (PMID 37393293, 2023). "Other oncogenic circuits can also exploit IGF2 production to sustain cancer cell stemness." (PMID 36672737, 2023). "Interestingly, the overactivation of the IGF-2/IR-A loop in cancer cells is a mechanism of adaptive resistance to anti-IGF-1R drugs." (PMID 37834454, 2023). "Finally, the Insulin-like growth factors 1 and 2 (IGF-1 and IGF-2) are directly involved in cancer cell expansion, and their bioactivity can be modified by specific IGF-binding proteins (IGFBPs)." (PMID 37637416, 2023). "Given the cumulative evidence displaying such wider preference for IGF2-p3 by established oncogenic TFs, a new class of gene therapies targeting IGF2-p3’s function may bear a distinctive advantage in cancer therapeutics." (PMID 37371750, 2023). "However, further studies are needed to demonstrate the exact relevance of inhibiting FOXO1 transcriptional activity in promoting the stem-like phenotype of IGF2 in cancer." (PMID 36672737, 2023). "IGF2 overexpression increased glucose consumption, increased lactate production, and increased the mRNA expression of glucose and lactate transporters and glycolytic enzymes involved in cancer development and progression." (PMID 37559065, 2023). "Despite its importance, little is known about IGF2’s role in carcinoma." (PMID 37393293, 2023). "Similar to H19, IGF2 is also highly active in various human cancers." (PMID 36246634, 2022). "Increased expression of IGF-2 and the consequent over-activation of this pathway by both insulin and IGF-2 is highly prevalent in cancer cells and may represent an important factor of resistance to various anti-cancer drugs." (PMID 35017650, 2022). "Also, it was discovered that cancer cell-secreted IGF2 instigates fibroblasts and bone marrow-derived vascular progenitor cells to promote cancer progression." (PMID 35651785, 2022). "Upregulated genes in mEPCs, including IGF2, GPC3, S100A4, STMN1, and MDK, were semi-automatically assigned to the traditional cancer hallmark framework 15, including proliferative signaling, invasion/metastasis, genomic instability, immune response, and stem cell-like program." (PMID 36198671, 2022). "This study suggests that a TUG1–miR-148b–IGF-2 pathway might have an oncogenic role in some cancers." (PMID 35597813, 2022). "IGF2 is an essential glucose regulatory factor that promotes the proliferation of several cancers." (PMID 35391781, 2022). "In epidemiological studies, there is no clear association between IGF2 serum levels and cancer risk." (PMID 34440844, 2021).
cancer (continued). "A recent report in colorectal cells indicates that IGF2 LOI might favor cancer stem cells pluripotency by promoting autophagy, through IGF2-dependent activation of the overexpressed IR-A." (PMID 34440844, 2021). "IGF2 has oncogenic activity and is overexpressed in diverse types of cancers, including HCC36." (PMID 33293585, 2020). "Interestingly, an IPA analysis showed that different regulated genes were positively associated with the invasion and migration process in cancer cells: VCAN, SPARC, IL6, MMP14, IL4R, ICAM, TIMP1 and IGF2." (PMID 32848147, 2020). "It is also remarkable that IGF-2 is known to play an important role during fetal growth and development, and its expression in malignant tumors might implicate a more primitive cellular phenotype." (PMID 33114046, 2020). "IGF2/IGF2R interaction influences cell growth, survival, and migration in normal tissue development, and the deregulation of IGF2R expression has been associated with growth-related disease and cancer." (PMID 32075092, 2020). "IGF-2 promotes excessive growth and anti-apoptotic effects in cancer cells." (PMID 33114046, 2020). "In addition, we noticed that cancer cells possessing more CNVs seemed to express higher levels of IGF2." (PMID 33033240, 2020). "Understanding the mechanism of drug resistance and the role of IGF-2 inhibitors in its formation may contribute to the development of a new therapeutic strategy in the fight against cancer." (PMID 32850012, 2020). "Aberrant IGF2 imprinting may be an intrinsic epigenetic control mechanism that enhances stemness, self-renewal and chemo/radiotherapy resistance in cancer stem cells." (PMID 33173015, 2020). "Moreover, ErbB2 can form heterodimers with IGF-IR in IGF-IR inhibitor-resistant cancer cells, leading to the induction of ErbB2 phosphorylation by IGF2." (PMID 32493414, 2020). "On the other hand, treatment of cancer cells with the anti-IGF-IR mAb cixutumumab paradoxically triggers cancer cells to produce IGF2, which in turn recruits macrophages and fibroblasts to promote angiogenesis and metastasis thereby hampering the efficacy of cixutumumab." (PMID 32493414, 2020). "It was previously shown that IGF2 promotes cancer development and progression." (PMID 31231466, 2019). "INSR-A is the main isoform in foetal tissues (e.g. foetal fibroblasts, muscle, liver and kidney) and in cancer, and binds insulin-like growth factor 2 (IGF-2) with high affinity, which elicits mitogenic effects, thereby contributing not only to organism development, but also to cancerous growth." (PMID 30559346, 2019). "IGF2 was an anti-apoptotic endocrine protein, and its upregulation existed in many cancers." (PMID 31133028, 2019). "We speculate that IGF2 expression is a potential biomarker of prior environmental exposures and stressors as well as heritable variations in metabolic and inflammatory pathways which interact to regulate IGF2 and cancer mortality in UCS." (PMID 29455465, 2018). "Furthermore, it is increasingly accepted that IGFBP6 is involved in abrogating the proliferation, migration, and survival of cancer cells by inhibiting IGF2." (PMID 30231881, 2018). "In cancer cells having an activated IR-A/IGF-2 loop, reduced MARCH1 levels could be responsible of the increased IR expression levels on the cells surface, thus potentiating the IR-mediated mitogenic effects." (PMID 30453495, 2018). "We also identified genes in CAPs that have been reported as actionable targets in cancer (e.g. IGF2 increased expression in CAPs), which suggests the possibility of therapeutic approaches that could result from our findings." (PMID 29453410, 2018).
cancer (continued). "Within the increased IR, in cancer the IR-A isoform is predominant, potentiating the cell proliferation, because of having a more marked mitogenic effect than IR-B, and also because having a high-affinity for IGF-2." (PMID 30453495, 2018). "LOI of IGF2 may be involved in the development of cancers because of its effects on cell proliferation and migration." (PMID 30073757, 2018). "The activated IGF-2/IR-A loop is associated with de-differentiation and stem-like phenotype and also in EMT and other stem-like features, which play a key role in cancer development and recurrence." (PMID 30453495, 2018). "Activated IR-A/IGF-2 loop may support the stem cell ability of self-renewal, promoting cancer cell survival and migration." (PMID 30453495, 2018). "Therefore, the role of the IGF2/IGF2R complex in cancer progression should be investigated in further studies." (PMID 30168002, 2018). "Although IGF2 and Nanog have been known to play an important part in regulating proliferation of cancer cells, it remains unclear as to how they cooperate in regulating proliferation of LSCs in AML." (PMID 30013477, 2018). "Moreover, some of markers were related to cancer progression, like IGF2, PTGS2, WNT3A, according to our literature review." (PMID 28415743, 2017). "In human cancer diseases, IGF2 is often epigenetically dysregulated." (PMID 29017567, 2017). "The selectivity of IGF2 for IR-A may be important in cancer and cancer treatment since many cancer types overexpress IR-A and secretes IGF2." (PMID 28570711, 2017). "IGF2 promotes proliferation in several cancer types and serves as an anti-apoptotic agent." (PMID 28230721, 2017). "Numerous studies provide evidence that hypomethylation of the IGF2-DMR0 might be also a potent reason for IGF2 LOI as well as for aberrant IGF2 expression, and thus, a predictive factor for cancer development." (PMID 29017567, 2017). "IGF1 and IGF2 are overexpressed in cancer and major therapeutic targets." (PMID 28873464, 2017). "Next, we investigated the paracrine effect of cancer cell-secreted IGF2 on fibroblasts." (PMID 28186102, 2017). "The selectivity of IGF2 for IR-A may be important in cancer and cancer treatment since some cancer cells express increased level of IR-A in combination with increased IGF2 expression." (PMID 28570711, 2017). "The reduction in cell viability induced by MIR494 has been observed in other cancer types; indeed, several MIR494 targets have been thus far identified which are associated with reduced cellular survival including IGF2, c-KIT, HOXA10, CLPTM1L, SCGN, CXCR4, and c-myc." (PMID 26794413, 2016). "As we previously reported, both the “C” and “T” alleles of IGF2 mRNA transcripts are present in non-CSCs, indicating loss of imprinting in this cancer cell line." (PMID 27275535, 2016). "IGF2BP3 may increase the cancer stem cell percentage through IGF2 in HCC, which probably lead to the stemness-related genes like CD133 and ABCB1 expression up-regulation." (PMID 26327240, 2015). "Cixutumumab treatment stimulates STAT3-dependent transcriptional upregulation of IGF-2 in cancer cells and recruitment of macrophages and fibroblasts via paracrine IGF-2/IGF-2R activation, resulting in the stroma-derived CXCL8 production, and thus angiogenic and metastatic environment." (PMID 26465273, 2015). "Collectively, IGF-2/INSR-A autocrine loop has been considered as an important signaling pathway in cancer stem cell biology, and INSR-A:INSR-B ratio may be important in the pluripotent phenotype of cancer cells." (PMID 26217584, 2015). "Our findings using TNBC models and archival specimens suggest that IGF-2 may regulate ERβ expression which in turn modulates metabolic and growth factor pathways in cancer progression." (PMID 25874233, 2015). "Altered IGF2 expression occurs in multiple neurodevelopment diseases and cancer." (PMID 25423083, 2014).
cancer (continued). "It is not clear whether IGF2 overexpression modifies the biology and growth of this cancer, thus more studies are required before IGF2 can be considered as a major therapeutic target." (PMID 25089899, 2014). "Since both IR-A and IR-B are regulated by insulin, IGF1 and IGF2 through autocrine and/or paracrine mechanisms, the microenvironment of the cancer site may also contribute to the relationship of HIR with clinical prognosis and patient survival." (PMID 24571613, 2014). "Both IGF-1 and IGF-2 enhance the proliferation of human cancer cells through IGF-1R and IR-A." (PMID 24171117, 2013). "Although the IGF2BP paralogue-specific regulation of IGF2 expression might well be regulated in a cell type- or cancer progression-dependent manner, these and various other findings indicate IGF2 as a key target transcript of the IGF2BP protein family." (PMID 23069990, 2013). "Among 35 primary serous epithelial ovarian cancer specimens, methylation of two CpGs, including one within the core binding motif and another adjacent to this motif, was higher in the 18 cancers with elevated IGF2 expression versus 10 with low expression (average 68.2 versus 38.5%; p < 0.0001)." (PMID 23745176, 2013). "Studies examining associations between environmental factors and epigenetic changes in IGF2 linked to various cancers are lacking." (PMID 24350186, 2013). "Our findings suggest a new role for PLAG1 in IGF2 overexpression in cancer." (PMID 23023303, 2012). "Dysregulation of IGF2, its receptors (the type 1 and 2 IGFR), and IGFBPs provide part of the underlying mechanism for uncontrolled increase in cellular proliferation, as is evident in cancer." (PMID 23023303, 2012). "CD222/ insulin-like growth factor-2 (IGF2R) has long been recognized as a cancer-expressed protein." (PMID 23251904, 2012). "LOI and increased expression of IGF2 are observed in many cancers including PCa." (PMID 23781309, 2012). "In the adult, igf2 loss of imprinting (LOI) and re-expression of IGF-II have been shown in cancer." (PMID 22970135, 2012). "Reports have shown that the CTCF target sites within the H19 ICR are de novo methylated in a wide range of human cancers, which would lead to prevention of CTCF binding and loss of insulator function at the maternal allele, followed by IGF2 allelic reactivation." (PMID 23023303, 2012). "To identify the paracrine factors responsible for T47D carcinoma cell growth stimulation we treated the co-cultures with neutralizing antibodies to eleven factors implicated in stroma-carcinoma interactions (FGF-2, HB-EGF, Heparanase-1, HGF, IGF-1, IGF-2, MT1-MMP, PDGF, SDF-1, TGF-β1, and Wnt-1)." (PMID 23056402, 2012). "These included Bmp7, Pparg and Igf2, all of which play an important role in cancer biology." (PMID 21464922, 2011). "IMP1 expression is stimulated by Wnt/β-catenin signaling and has many regulatory targets, some of which are implicated in cancer: stabilization of c-myc and CD44 mRNAs, translational suppression of IGF2, and localization of β-actin mRNA to sites of actin polymerization." (PMID 20860831, 2010). "Proliferin is a member of the prolactin family which is involved in progenitor cell expansion along the luminal and myoepithelial lineage and Igf2 plays a pivotal role in fetal and cancer development by signaling via the IGF-I and insulin receptors, and activating the estrogen-signaling cascade." (PMID 19450255, 2009). "IGF2BP2, a m6A reader protein, is a member of the IGF2 mRNA‐binding protein family that regulates various post‐transcriptional processes such as mRNA localization, stability, and translation by recognizing the m6A modifications on transcripts critical for cancer initiation and progression." (PMID 39948708, 2025). "Moreover, cancer patients with a high infiltration level of IGF2+ fibroblasts had a poor prognosis." (PMID 39545420, 2024).
cancer (continued). "The mechanisms by which diabetes predisposes individuals to cancer are not fully understood; however, researchers suggest that insulin-like growth factors (IGF-1 and IGF-2) and the stimulating effects of hyperglycemia on cancer cell proliferation may play significant roles." (PMID 39682196, 2024). "Furthermore, IGF2 played a role in a variety of cancer development." (PMID 39691708, 2024). "Importantly, even in healthy individuals, LOI of IGF2 is not uncommon and occurs with aging, yet it predicts cancer risk and was—in a murine prostate cancer model—found to be sufficient to increase the rate of neoplastic development on its own." (PMID 39199324, 2024). "IGF2 LOI has been found in the blood and tissues of both patients with CRC and healthy controls and may be a valuable predictive marker of an individual’s risk of carcinoma." (PMID 38812777, 2024). "Notably, in some benign and malignant tumors, IGF2 expression is directly regulated by Pleomorphic adenoma gene 1 (PLAG1), inducing autocrine IGF-1R signaling that leads to the activation of PI3K/AKT downstream cascade, enhancing cell survival and proliferation." (PMID 36901760, 2023). "This type of integrated approach to study IGF2 gene regulation both in IGF2 expression syndromes and in cancer, according to the authors of the present work, is essential in order to move the field beyond the historical (and still ongoing) compartmentalized approach to IGF2 gene studies." (PMID 37371750, 2023). "The cancer risk of chronic intranasal IGF2 administration is likely to be low, as well; 1 year of daily intranasal administration of insulin, which is also a mitogenic peptide, did not increase cancer incidence in a large clinical trial." (PMID 36971212, 2023). "Finally, for IGF2BP1, the oncofetal IGF2 mRNA binding proteins (IGFBPs) are upregulated in various cancer entities and have been shown to possess a distinct conservation of highly oncogenic potential throughout a panel of five cancer-derived cell lines." (PMID 37885041, 2023). "While this study was conducted in a cancer model with activating mutations of PI3K, it is likely that other mechanisms may contribute to PI3K activity, such as PTEN mutations or IR/IGF1R activation by autocrine IGF2." (PMID 36672737, 2023). "The urgent need is that of a combinatorial treatment wherein we could block the IGF-1R on one hand and also revert the splicing of IR-A back to the full-length IR-B so as to completely block the downstream mitogenic signaling of IGF-2 and suppress the cancer phenotype." (PMID 35017650, 2022). "Moreover, IGF1 and IGF2 mediate cancer cells’ resistance to paclitaxel in murine models, suggesting that lowered IGF bioavailability could heighten chemotherapy." (PMID 34073987, 2021). "However, the frequency of various cancers occurred more frequently in IGF2 transgenic mice." (PMID 34200243, 2021). "Thus, IGF2 transcripts generated from P1 may preferentially respond to factors activated by rapidly growing cells such as hepatocytes and cancer cells." (PMID 33216823, 2020). "So far, however, only a small number of known cancer-associated lncRNAs have been found to be regulated by the interaction with RBPs like human antigen R (HuR), ARE/poly(U)-binding/degradation factor 1 (AUF1), insulin-like growth factor 2 mRNA-binding protein 1 (IGF2BP1), and tristetraprolin (TTP)." (PMID 32340118, 2020). "H19 is closely linked to insulin-like growth factor-2 (IGF2) gene which is also located in the region subjected to imprinting by methylation and plays a crucial role in the normal growth and development of the fetus and also important in cancer occurrence and progression." (PMID 32509581, 2020). "IGF2 binds with high affinity (similar to that of insulin) to IR-A, amplifying mainly the mitogenic but not the metabolic effect and may play a role in both fetal growth and cancer biology." (PMID 31623387, 2019).